NOTCH1 (notch receptor 1)
Diseases named in the same sentence as NOTCH1 in open-access papers (continued):
Sharing a sentence is not in itself a finding about the gene and the disease.
osteosarcoma (continued). "overexpressed CRNDE lncRNA functions as oncogene in osteosarcoma cells via upregulation of Notch1, JAG1 and EMT related proteins." (PMID 36229883, 2022). "As showing in the results, we found that silencing CEMIP significantly decreased the protein expression of Notch receptor Notch1, Notch ligand Jagged1, and Notch target gene Hes1 in osteosarcoma cells." (PMID 35957875, 2022). "Exposure of osteosarcoma cells to sub-lethal doses of doxorubicin upregulated Notch1 signaling and promoted the EMT, whereas treatment with GSI was able to prevent these changes." (PMID 34680255, 2021). "Taken together, our findings provide an alternative strategy of combining regulators of Notch1 expression to treat osteosarcoma." (PMID 34495871, 2021). "Curcumin has been shown to inhibit hypoxia-induced HIF-1α expression by downregulation of Notch1 expression and acts as a potential anti-cancer agent for the treatment of osteosarcoma." (PMID 34671398, 2021). "In the present study, human osteosarcoma cell lines were treated with a Notch1 inducer, and changes in cell proliferation, the cell cycle and autophagy were analysed." (PMID 34495871, 2021). "In conclusion, their results demonstrated that curcumin exerts an inhibitory effect on osteosarcoma cell proliferation and invasion by inhibition of Notch-1 signaling, following the suppression of Hes-1, cyclin D1, MMP-2, and MMP-9 expression." (PMID 34671398, 2021). "Better understanding of how Notch1 regulates PI3K/Akt/mTOR would likely create novel therapeutic opportunities for targeting these important cellular pathways in osteosarcoma." (PMID 34495871, 2021). "To investigate the effect of Notch1 on osteosarcoma cell growth and autophagy, we developed an in vitro model of doxycycline-induced expression of NICD1 using the TET-ON system, which was based on the tetracycline-controlled transactivator protein tTA." (PMID 34495871, 2021). "The aim was to investigate changes in autophagic activity and the molecular mechanism of Notch1-mediated PI3K/Akt/mTOR signalling during autophagy to provide a theoretical basis for the treatment of osteosarcoma." (PMID 34495871, 2021). "Flow cytometry and cell apoptosis analysis were conducted to measure the effect of Notch1 on the cell cycle of human osteosarcoma cells." (PMID 34495871, 2021). "Our study showed that high expression of Notch1 positively correlated with active autophagy in human osteosarcoma cells." (PMID 34495871, 2021). "Mechanistically, they found SEs function as an activator of the NOTCH1 pathway through regulating the LIF/STAT3 pathway in promoting the progression of osteosarcoma." (PMID 32714929, 2020). "Notch1 was significantly upregulated in osteosarcoma tissues and cell lines and was negatively correlated with the expression levels of miR-92a." (PMID 29984257, 2018). "According to Zhang and colleagues, HES1 can directly downregulate Dtx1, which is acting as a negative regulator of Notch1 signaling, through degradation of the intracellular domain of Notch1 in osteosarcoma." (PMID 28122586, 2017). "Our data showed that the Notch signaling pathway, and Notch1 in particular, plays a key role in the maintenance of osteosarcoma stem cells and cisplatin chemoresistance." (PMID 27102300, 2016). "In vitro study confirmed this finding that osteosarcoma cell line Saos-2 with higher Notch1 expression was more sensitive to cisplatin than MG63 with lower Notch1 expression." (PMID 24894297, 2014). "In contrast, sample from the recurrent osteosarcoma were insensitive (inhibition rate: 0.00%) to cisplatin treatment with low Notch1 and HES1 expression." (PMID 24894297, 2014). "Activation of Notch1 signaling pathway significantly sensitized osteosarcoma cells to cisplatin treatment while inhibition of Notch1 signaling pathway desensitized these cells to cisplatin." (PMID 24894297, 2014). "Our findings showed that Notch1 signaling pathway had a positive correlation with cisplatin sensitivity in osteosarcoma." (PMID 24894297, 2014).
osteosarcoma (continued). "Taken together, we demonstrated that suppression of Notch1 signaling pathway desensitized osteosarcoma cells to cisplatin treatment." (PMID 24894297, 2014). "Overall, our study comprehensively revealed that the expression of Notch1 was positively correlated with cisplatin sensitivity in osteosarcoma." (PMID 24894297, 2014). "Together, these results suggested that the activation of Notch1 signaling pathway sensitized osteosarcoma cells to cisplatin treatment." (PMID 24894297, 2014). "To better understand the effect of Notch1 signaling pathway on cisplatin-sensitivity in osteosarcoma, we examined the apoptosis rate induced by cisplatin." (PMID 24894297, 2014). "Notch1 signaling pathway can be used as a molecular marker for cisplatin sensitivity in osteosarcoma patients." (PMID 24894297, 2014). "The relationship between Notch1 expression and cisplatin sensitivity of osteosarcoma patients was detected by immunohistochemistry and semi-quantitative analysis." (PMID 24894297, 2014). "In order to verify the positive relationship between the expression of Notch1 and cisplatin sensitivity in osteosarcoma, two osteosarcoma cell lines, Saos-2 and MG63, were analyzed in vitro." (PMID 24894297, 2014). "DLX5 exerts oncogenic effects in osteosarcoma through NOTCH1 activation, and given that the Notch pathway drives TGF-β–induced EMT, DLX2 may contribute to EMT through similar mechanisms." (PMID 41244921, 2025). "Another study revealed that KIAA1429-dependent m6A methylation could repress miR-143-3p and increase the expression of its target gene, NOTCH1, leading to proliferation, migration and invasion of osteosarcoma cells." (PMID 40180675, 2025). "Similarly, the co-administration of DOX with cisplatin or knockdown of Notch1 in osteosarcoma reduced the cytotoxic effects of DOX via the unanticipated upregulation of Notch1 and related target genes." (PMID 40427168, 2025). "In addition, ALKBH5-induced m6A demethylation suppresses growth, migration, and invasion of osteosarcoma cells by enhancing the RNA stability of NOTCH1 and NOTCH2." (PMID 40180675, 2025). "In addition, a study reported that the low expression of NOTCH1 significantly correlated with low sensitivity to cisplatin in osteosarcoma specimens." (PMID 36975516, 2023). "In addition, studies have reported that the activation of NOTCH1 signaling induced by cisplatin promoted the activity of CSCs in osteosarcoma in vitro, including increasing the number of Stro-1+/CD117+ double-positive cells and spheroid formation capacity." (PMID 36975516, 2023). "A cohort study of 12 patients with osteosarcoma revealed that the NOTCH1 signaling pathway was significantly upregulated in tumor tissues, and the high expression of the NOTCH1 intercellular domain (NICD1) and the NOTCH target gene Hes1 was associated with a poor response to chemotherapy." (PMID 36975516, 2023). "A study found that the osteosarcoma LM-7 cell line, which showed highly invasive and metastatic features, markedly upregulated the expression of NOTCH1, NOTCH2, Dll1, and Hes1 compared with normal human osteoblasts and the Saos-2 cell line with low metastatic potential." (PMID 36975516, 2023). "Blocking NOTCH1 signaling could effectively reverse the EMT phenotype of osteosarcoma cells induced by low concentrations of DDP, resulting in the attenuation of migration and invasiveness." (PMID 36975516, 2023). "Doxycycline-induced Notch1 activation also induced apoptosis and autophagy in osteosarcoma cells." (PMID 34495871, 2021). "Annexin V-FITC/PI double staining demonstrated that osteosarcoma cells activated the Notch1 pathway in a time-dependent manner after treatment with doxycycline in both early and late apoptotic cells, in which the proportion of apoptotic cells increased from 5.3% to 33.8%." (PMID 34495871, 2021). "Our study aimed to investigate the role of Notch1 in osteosarcoma development." (PMID 34495871, 2021).
osteosarcoma (continued). "Further results showed that overexpression of Notch1 could inhibit osteosarcoma cell proliferation and improve apoptosis and autophagy by regulating the PI3K/Akt/mTOR pathway." (PMID 34495871, 2021). "At the same time, consistently with the quite equivocal benefits of combining Notch inhibition with cisplatin for osteosarcoma treatment, knockdown of Notch1 in this tumor model reduced the cytotoxic effects of doxorubicin partially related to the upregulation of Notch1 and its target genes." (PMID 34680255, 2021). "We then determined whether Notch1 induced by 10 μM doxycycline could induce autophagy in osteosarcoma cells." (PMID 34495871, 2021). "The present study proves that Notch1 induces osteosarcoma apoptosis." (PMID 34495871, 2021). "Moreover, curcumin inhibited growth and invasion of osteosarcoma cells through downregulation of Notch1 and matrix metallopeptidase (MMPs), and in oral SCC, it reduced the expression of Notch target genes such as MMPs, BCL-2 and NF-κB." (PMID 34680255, 2021). "In addition, lncRNA NBR2 is downregulated in osteosarcoma tissues and serves as a tumor suppressor gene by directly binding the Notch1 protein, thereby decreasing Notch1 mRNA expression and increasing E-cadherin mRNA expression." (PMID 31575017, 2019). "We confirmed that cisplatin-induced enrichment of osteosarcoma stem cells was mediated through Notch signaling in vitro, and immunohistochemistry showed that cleaved Notch1 (NICD1) positive cells were significantly increased in a relapsed xenograft which had received cisplatin treatment." (PMID 27102300, 2016). "Interestingly, sample from the primary osteosarcoma were sensitive to cisplatin treatment (inhibition rate: 54.28%) with higher Notch1 and HES1 expression." (PMID 24894297, 2014). "Our data clearly demonstrated that Notch1 is critical for cisplatin sensitivity in osteosarcoma." (PMID 24894297, 2014). "As ADAM10 is a major regulator of Notch signaling via its shedding of Notch receptors, we sought to determine whether increased expression of ADAM10 in osteosarcoma progression would also lead to increased activation of Notch1." (PMID 24548763, 2014). "On the contrary, we speculated that activation of Notch1 signaling pathway would have the opposite effect on the expression and/or activity of Caspase family proteins, which could lead osteosarcoma more sensitive to cisplatin." (PMID 24894297, 2014). "Therefore, this study aims to determine the roles of Notch1 signaling pathway in osteosarcoma, as well as the mechanisms of cisplatin response in osteosarcoma." (PMID 24894297, 2014). "Collectively, these results indicated that Notch1 activation might enhance cisplatin induced osteosarcoma cell apoptosis." (PMID 24894297, 2014). "Notch1 may be a potential clinical antitumour target for osteosarcoma therapy." (PMID 34495871, 2021). "Mir-92a could inhibit the growth and the migration of osteosarcoma cells through targeting Notch1." (PMID 35087570, 2021). "Our study proved that Notch1 signaling pathway whose activity changes might directly or indirectly affect the expression and activity of Caspase family proteins was also a possible key regulator for cell apoptosis induced by cisplatin in osteosarcoma." (PMID 24894297, 2014). "Thus, Notch1 could be an effective molecular marker for predicting and even regulating the cisplatin sensitivity in osteosarcoma patients." (PMID 24894297, 2014). "Similarly, we would speculate that the activation of Notch1 signaling pathway may retain osteosarcoma cells in an undifferentiated stage, in which cell division and DNA replication process may be more frequent." (PMID 24894297, 2014). "Tetrahydroxycurcumin inhibits Notch‐1's signaling pathway and its downstream target gene, matrix metalloproteinase (MMP), as part of its new method of action on osteosarcoma cells." (PMID 41179371, 2025).
osteosarcoma (continued). "To validate interactions and physical closeness of HDAC1 and NOTCH1 proteins in cells using an additional approach, we performed in situ proximity-based ligation assay (PLA) in human SJSA-1 osteosarcoma cells." (PMID 38043798, 2024). "Curcumin treatment suppressed invasion in human osteosarcoma U2OS cells, and overexpressing Notch1 reversed this effect, indicating that the antitumor effect of curcumin is mediated through Notch1." (PMID 39092224, 2024). "A study found that the expressions of NOTCH1, NOTCH2, Hes1, and Hey1 increased markedly in primary canine osteosarcoma." (PMID 36975516, 2023). "For instance, at non-toxic doses, doxorubicin seems to inhibit the proliferation of osteosarcoma cells via the up-regulation of target genes such as HEY1, NOTCH1, HES1, and HES5." (PMID 37176108, 2023). "Curcumin has been demonstrated to downregulate Notch1 expression, hindering hypoxia-induced HIF-1 expression and acting as a possible anticancer drug for treating osteosarcoma." (PMID 36297027, 2022). "Studies revealed that Notch pathway genes including Notch1, Notch2, Notch ligand DLL1, and Notch target genes including Hes-1, Hey-1, and Hey-2 were expressed in osteosarcoma cells." (PMID 34671398, 2021). "The results showed that doxycycline-induced Notch1 increased the levels of LC3B-II and Beclin-1 in osteosarcoma cells in a time-dependent manner." (PMID 34495871, 2021). "Therefore, we concluded that inhibition of Notch1 signaling pathway even with cisplatin treatment in osteosarcoma cells might directly or indirectly decrease the expression and/or activity of Caspase family proteins, generally leading to reduced sensitivity to cisplatin at last." (PMID 24894297, 2014). "Another study also found that HEY1 and other downstream target genes of Notch signaling including HES1, NOTCH1 and NOTCH2, were elevated in canine osteosarcoma by gene expression microarray analysis and reverse transcriptase - quantitative PCR (RT-qPCR)." (PMID 25023069, 2014). "In agreement with our results, it has been shown that suppression of NOTCH1 inhibits tumor growth in human HCC and in osteosarcoma by regulating cell proliferation and cycle." (PMID 24885920, 2014). "In our study, we for the first time identified that the expression of Notch1 and HES1 in osteosarcoma specimens were positively correlated with cisplatin sensitivity in osteosarcoma patients." (PMID 24894297, 2014). "Recent studies show that distal-less homeobox (DLX) 5 binds directly to the Notch1 promoter, which triggers upregulation of gene transcription in osteosarcoma cells, and that SIRT6 epigenetically regulates Notch1 transcription via DNA methyltransferase (DNMT) 1 in adipose-derived stem cells." (PMID 36593298, 2023). "NBR2 acts as tumor suppressor by inhibiting Notch1 expression in NSCLC and osteosarcoma." (PMID 36229883, 2022). "It was revealed that VIRMA knockdown could suppress the expression of stem factors Notch1, Oct4, Nanog and CD44 in osteosarcoma cells, which suggested that VIRMA promoted osteosarcoma progression by activating Notch signaling pathway." (PMID 33731118, 2021). "Thus, PI3K/Akt/mTOR signalling is central to the Notch1 signalling pathway, suggesting that targeting PI3K/Akt/mTOR with small molecule inhibitors would show great promise in treating osteosarcoma." (PMID 34495871, 2021). "In osteosarcoma cells, Notch1 expression is absent, and the Notch1 pathway is related to cancer cell proliferation, apoptosis and autophagy." (PMID 34495871, 2021). "Furthermore, in osteosarcoma, overexpression of CRNDE enhanced Notch1 signal transduction activity and promoted EMT programme, Notch1, JAG1, N-cadherin and vimentin were upregulated, while CRNDE knockdown produced the opposite effects." (PMID 32435153, 2020). "We have previously shown that the osteosarcoma cell line K7M2 actively expresses Notch genes (Notch1, Notch2, and Notch4; Hes1), but not Notch3." (PMID 27378829, 2016).
osteosarcoma (continued). "Notch1 was activated in osteosarcoma tissue at all stages; however, its activation was not significantly correlated with pathological staging, as shown by NICD density from stage IB to stage IIB." (PMID 24548763, 2014). "The expression of CD31 and activation of Notch1 did not dramatically contribute to osteosarcoma progression overall." (PMID 24548763, 2014). "Jag1-mediated NOTCH1 signaling promoted ERK phosphorylation, resulting in increased proliferation and migration of K7M2 cells, while non-selective NOTCH inhibitors significantly inhibited the invasion and migration of osteosarcoma cells by decreasing ERK phosphorylation." (PMID 36975516, 2023). "Authors assessed the antitumor activity of curcumin using three different osteosarcoma cell lines (U2OS, SaOS-2, and MG-63), to see whether downregulation of Notch-1 is critical in curcumin-induced inhibition of proliferation and invasion in osteosarcoma cells." (PMID 28773642, 2016). "However, the roles of Notch1 signaling in osteosarcoma and chemotherapy response have not been elucidated yet." (PMID 24894297, 2014). "Subsequently, two typical osteosarcoma cell lines, Saos-2 and MG63, were selected to study the changes of cisplatin sensitivity by up-regulating (NICD1 plasmid transfeciton) or decreasing (gamma-secretase complex inhibitor DAPT) the activation state of Notch1 signaling pathway." (PMID 24894297, 2014). "Therefore, as one of four members in the mammalian Notch receptor family, Notch1 might not be the Notch receptor responsible for osteosarcoma progression." (PMID 24548763, 2014). "Tissue chip samples from 40 cases of nonmetastatic osteosarcoma were stained for cytoplasmic ADAM10, activated Notch1 and CD31." (PMID 24548763, 2014). "The goal of our present study was to investigate the expression of ADAM10, Notch1, CD31 and tartrate-resistant acid phosphatase (TRAP) in nonmetastatic osteosarcoma tissue and their respective contributions to tumor progression." (PMID 24548763, 2014). "In our present study, we examined the expression of CD31, ADAM10, Notch1 and TRAP in nonmetastatic osteosarcoma tissue chips." (PMID 24548763, 2014). "Although, it was recently reported that DLL1, Notch1, Notch2, and HES1 are expressed in osteosarcoma cell lines, whether expression of Notch signalling molecules in osteosarcoma patient specimens is aberrant has not been clarified." (PMID 19455146, 2009).